GATA5 (GATA binding protein 5)
Diseases named in the same sentence as GATA5 in open-access papers (continued):
Sharing a sentence is not in itself a finding about the gene and the disease.
tumor (27 papers, 2007 to 2025). "In lung cancer, aberrant promoter DNA methylation leads to a loss of GATA4 and GATA5 activity as tumor suppressor genes." (PMID 34827720, 2021). "Our results underline the need for further functional studies to characterize the interaction of GATA5 and cellular signaling in ccRCC with respect to the observed changes in expression and methylation levels, and its association with tumor progression." (PMID 24533449, 2014). "Epigenetic alterations of GATA5 were also described in other tumor tissues and were linked to the development of ovarian, lung, pancreatic, and esophageal cancer." (PMID 24533449, 2014). "The associations between GATA5 subgroup and BMI, and GATA5 subgroup and smoking remained statistically significant even after adjusting for sex and tumor site (p = 0.03 and 0.04 respectively)." (PMID 22028801, 2011). "Our comparison of the mRNA and miRNA expression profiles of mutated and wild‐type KMT2D suggested that two signaling pathways (FOX1–miR‐1224‐5p–DLK1 and HIF/GATA5–miR‐133a‐3p–DRD5) may mediate the tumor suppressive effect of the KMT2D mutation." (PMID 30984543, 2019). "In one study, methylation of the GATA5 CpG island was identified as a potential biomarker for tumor progression." (PMID 41514651, 2025). "GATA5 functions as a tumor suppressor in prostate cancer by inhibiting its progression through the regulation of PLAGL2 through FAK/AKT/PI3K pathway." (PMID 41514651, 2025). "GATA5 expression was significantly downregulated in adjacent non-tumor tissues from AA men compared to EA men." (PMID 38566104, 2024). "The tumor size and tumor growth rate in the pc-GATA5 group were significantly smaller and lower than those of the pc-vector group." (PMID 35565203, 2022). "Research has also shown that GATA5 can suppress the tumor progression by downregulating the Wnt/β-catenin signaling pathway and inhibiting reprogramming genes." (PMID 35565203, 2022). "GATA4 and GATA5 tend to mark fully differentiated epithelial cells and confirmed as potential tumor suppressors, while GATA6 expresses in the immature proliferating cells in the intestinal crypts and classified as potential oncogene." (PMID 35488350, 2022). "Altered expression of GATA4, GATA5, and GATA6 are associated with abroad range of tumours emerging from the gastrointestinal tract, lungs and brain." (PMID 35488350, 2022). "We found overexpression GATA5 inhibited tumor proliferation, migration, invasion and the process of epithelial–mesenchymal transition (EMT), and upregulation of GATA5 promoted PCa cell apoptosis." (PMID 35565203, 2022). "Of these 13 gene candidates, three genes are already known to be tumor suppressor genes —adherens junctions associated protein 1 (AJAP1), GATA binding protein 5 (GATA5), and lecithin retinol acyltransferase (LRAT)." (PMID 33920410, 2021). "This study demonstrates that an increase in the expression of GATA5 inhibits the expression of β‐catenin and reprogramming genes and suppresses tumour growth, colony formation, metastasis and invasion, while promoting apoptosis in HCC cells." (PMID 30672133, 2019). "Surprisingly, we uncovered two signaling pathways leading to tumor suppression in the mutation group, FOX1–miR‐1224‐5p–DLK1 and HIF/GATA5–miR‐133a‐3p–DRD5." (PMID 30984543, 2019). "The analyses of relative GATA5 mRNA expression levels revealed significantly decreased expression in tumor specimens (TU; mean lnRQ = −1.7; ±SD = 1.63) compared with the corresponding adN (mean lnRQ = 1.73; ±SD = 1.32; p < 0.001; paired t-test)." (PMID 24533449, 2014). "The corresponding analysis of GATA5 methylation also demonstrated higher methylation in tumor tissues both for the RCC group (P<0.001) and the ccRCC subset (P<0.001)." (PMID 24549248, 2014). "We observed a noticeable difference of approximately two orders of magnitude in the median relative methylation values detected for GATA3 and GATA5 CGIs in tumor compared to adjacent normal renal tissues." (PMID 24549248, 2014).
tumor (continued). "In a recent study aimed at identifying new DNA methylation targets in ccRCC, we detected tumor-specific hypermethylation of the GATA5 CGI in RCC." (PMID 24533449, 2014). "In a recent study aimed at identifying new DNA methylation targets in ccRCC, we detected for the first time a tumor-specific hypermethylation of the GATA5 CpG island (CGI) in RCC." (PMID 24533449, 2014). "The mean relative GATA5 mRNA expression level exhibited an approximately 31-fold reduction in tumor specimens compared with corresponding normal tissues (p < 0.001, paired t-test)." (PMID 24533449, 2014). "Comparison of GATA3 and GATA5 methylation in different tumor cell lines revealed a marker-specific methylation characteristic with high and frequent signals for both methylation marks in RCC lines." (PMID 24549248, 2014). "A subgroup of tissues showed only moderate reduction of expression, although GATA5 methylation was detectable, indicating that other biological mechanisms, e.g. histone alterations, play a role in tumor development in ccRCC." (PMID 24533449, 2014). "Comparison of GATA3 and GATA5 methylation in matched tumor (TU) and adjacent normal (adN) tissues demonstrated tumor-specific hypermethylation." (PMID 24549248, 2014). "We defined the DNA methylation subgroups using the GATA5 cut point of 81.4 identified using the 45 tumor samples in the cluster analysis." (PMID 22028801, 2011). "A panel of four genes that included p16, DAPK, PAX5 β, and GATA5 was methylated in 77% of tumours and had a combined positive predictive value of 86%." (PMID 17406356, 2007). "Importantly, Sox11-dependent expression of a selection of genes from bulk RNA-seq clusters 1, 2, and 8, and of the tumor suppressor Gata5, a paralog of Gata4, had already been proven by targeted by qRT-PCR analyses, or was newly confirmed." (PMID 40393982, 2025). "Additionally, we observed an inverse correlation between DNA methylation and gene expression in annotated GATA5 transcription start sites in adjacent non-tumor tissues from AA men (middle and right panels: left bottom quadrant)." (PMID 38566104, 2024). "In contrast, the expression of genes, including STAG3, GATA5, and CACNB2, which are associated with cell proliferation or tumorigenesis, and PRAP1, which is primarily involved in the inhibition of tumor cell apoptosis, increased in mouse KrasG12D/Galc KO pancreatic organoids." (PMID 37848935, 2023). "We found that the methylation level of GATA5 promoter was higher in tumor tissues, so the 5-Aza-CdR, a methyltransferase inhibitor, was treated in PCa cells to verify this hypothesis." (PMID 35565203, 2022). "Overall, these data demonstrated that GATA5 is downregulated in both tumor tissues and cell lines." (PMID 35565203, 2022). "Thus, GATA4 and GATA5 is currently considered potential tumour suppressors, however, GATA6 can be used as a potential oncogene." (PMID 35488350, 2022). "Our study disclosed for the first time that GATA5 plays a role in tumor-inhibiting effects on PCa." (PMID 35565203, 2022). "Furthermore, analysis of 52 paired samples in TCGA also indicated that GATA5 was downregulated in PCa tissues in contrast with adjacent tumor tissues." (PMID 35565203, 2022). "Moreover, studies have identified some GATA family members, specifically GATA4, GATA5, and GATA6, as tumor suppressor genes associated with several cancer diseases." (PMID 34827720, 2021). "Epigenetic alterations in GATA family members may be associated with aggressive tumor phenotypes in RCC, and in the case of GATA5, may serve as a new independent molecular marker for aggressiveness and disease progression." (PMID 24549248, 2014). "Hypermethylation of GATA5 in RCC indicated that the expression of GATA5 might be epigenetically silenced in tumor cells, leading to a biologically more aggressive tumor phenotype." (PMID 24533449, 2014). "Furthermore, GATA5 CGI methylation exclusively demonstrated a statistical association with grade and lymph node status of the primary tumor." (PMID 24549248, 2014).
tumor (continued). "In addition, GATA5 showed a significantly higher CGI methylation status in the high-grade tumor and positive lymph node metastasis (N+) groups compared to low-grade tumor tissues (P=0.003) or negative lymph node status (P=0.03)." (PMID 24549248, 2014). "Using a PMR cut point of 81.4, GATA5 could predict whether a tumor belonged to Group 1 with 92.6% sensitivity and 94.4% specificity." (PMID 22028801, 2011). "Moreover, the association between the GATA5 subgroup and BMI and smoking remained statistically significant even after adjusting for sex and tumor subtype when subjects rather than samples were used in the analysis." (PMID 22028801, 2011). "Previously, we described a prognostic model comprising five DNA methylation markers (i.e., GREM1, GATA5, LAD1, NEFH, and NEURL) in combination with clinicopathological characteristics (i.e., age at diagnosis, sex, Fuhrman grade, tumor size, and TNM stage)." (PMID 40820938, 2025). "However, our finding showing a lack of association between the GATA5 methylation or GATA5 methylation-based groups and the degree of tumor differentiation does not support this hypothesis." (PMID 22028801, 2011). "Previously, we developed a prognostic biomarker model containing five DNA methylation markers (GREM1, GATA5, LAD1, NEFH, and NEURL) in combination with clinicopathological characteristics including age at diagnosis, sex, Fuhrman grade, tumor size, and TNM 3rd edition staging system." (PMID 40820938, 2025). "There was a significant negative correlation between DNA methylation of the GATA5 transcription start site and RNA expression in tumor tissue of EA men (middle and right panels: left top quadrant)." (PMID 38566104, 2024). "The results indicated that the expression of GATA1, GATA4 and GATA6 remarkably varied across the tumor stages, whereas GATA2, GATA3 and GATA5 demonstrated no significantly changes in different tumor stages." (PMID 34093794, 2021). "Methylation of GREM1, GATA5, LAD1, NEFH, NEURL, and SFRP1 was associated with poor ccRCC-specific survival, independent of age, sex, tumor size, TNM stage or tumor grade." (PMID 33947447, 2021). "A pairwise bivariate Cox regression model demonstrated that the GATA5 CGI methylation status remained a significant and strong parameter in the bivariate models when the status of metastasis, advanced tumor disease, grade, and age were considered as co-variables (Table IVB)." (PMID 24549248, 2014). "CNGs associated with poor outcome harboured transcription factors GATA3, GATA5, MLLT10, and TAF3 frequently amplified in HBCs15,19,28,41–43, EMT markers VIM, LAMA5, and ZEB121, and several genes enriching biological processes enhancing tumour-cell migration and motility." (PMID 31969654, 2020). "However, expression of GATA5 or GATA6 proteins in tumor or peritumor tissues was not correlated with pivotal clinicopathologic factors." (PMID 24498120, 2014).
cancer (19 papers, 2011 to 2023). A tumor composed of atypical neoplastic, often pleomorphic cells that invade other tissues. "Other genes that have been identified in the sputum with aberrant methylation associated with increased risk for lung cancer include ASC/TMS1 (increased odds in cancer patients from 7.2 to 28.6), GATA4, GATA5 and PAX5β (6.5-fold increase in cancer risk with methylation of three or more genes)." (PMID 23870182, 2013). "Furthermore, GATA5 is associated with malignant transformation in several types of human cancers." (PMID 35358005, 2022). "GATA5 belongs to the GATA gene family and is associated with a variety of diseases, including cancer." (PMID 35565203, 2022). "GATA5 is located at chromosome 20q13, a locus which is often amplified and methylated in multiple cancer types, including LC 56-58." (PMID 34093794, 2021). "In previous studies, the reduction of GATA4 and GATA5 expression in various human cancers, including HCC, was shown to be due to gene promoter methylation in various human cancers, including HCC." (PMID 30672133, 2019). "GATA5 is located at chromosome 20q13, a locus which is often amplified andmethylated in multiple cancer types." (PMID 26953528, 2016). "Transcriptional inactivation and CpG island (CGI) methylation of GATA transcription factor family members GATA3 and GATA5 have been reported for a few types of human cancer." (PMID 24549248, 2014). "The present study identified GATA3 and GATA5 methylation as a common and cancer-specific event in RCC." (PMID 24549248, 2014). "The loss of expression of the GATA family is associated with several cancers; loss of expression for GATA-4 and GATA-5, in particular, have been reported in CRC." (PMID 22852817, 2012). "Besides, as a transcription factor, GATA5 was found to suppress the progression of many human cancers." (PMID 35040754, 2022). "GATA5 is a transcription factor that inhibits the development of various human cancer types." (PMID 35040754, 2022). "It is interesting to note that GATA5 is one of the genes targeted by the Polycomb group for transcription repression in human embryonic stem cells, of which a large majority of genes become abnormally hypermethylated in cancers." (PMID 22028801, 2011). "In the present study, we also found that GATA5 synergized with Paclitaxel to inhibitexpression of the stemness markers CD44 and CD133 in the cancer stem cells." (PMID 32779438, 2020). "To investigate how GATA5 mechanistically stimulated Paclitaxel to suppress malignantbehaviors of HCC cells, we analyzed expression of the cancer stem cell reprogramminggenes, Nanog, EpCAM, c-Myc and Sox2 in the cells by Western blotting." (PMID 32779438, 2020). "Interestingly, all GATA family members besides GATA3 were mostly downregulated in most kinds of cancers, with upregulated vs downregulated study numbers (GATA1 1:7; GATA2 6:39; GATA3 31:36; GATA4 5:18; GATA5 1:17; GATA6 16:37)." (PMID 30872657, 2019). "Many studies have demonstrated the diagnostic efficiency of DNA hypermethylation of a variety of well-known cancer-related genes, such as p16, RASSF1, APC, MGMT, DAPK, GATA5, and HOX9, in various biofluids, including bronchial aspirates, sputum, serum, plasma, and cell-free circulating DNA." (PMID 27924164, 2016). "The large spectrum of cancers in which GATA5 DNA methylation has been documented suggests that GATA5 DNA methylation is not cancer type specific." (PMID 22028801, 2011). "Notably, these 3 smoking-associated markers even outperformed a methylation panel of 6 cancer-related genes (p16, MGMT, DAPK, RASSF1A, PAX5- β, and GATA5) assessed in sputum samples collected 3 to 18 months prior to LC diagnosis (sensitivity and specificity of 64%)." (PMID 27924164, 2016).
cancer (continued). "KEGG pathway analysis has indicated that GATA5 may regulate PCa progression through the focal adhesion kinase (FAK) signaling pathway, which participates in multiple fundamental processes, including angiogenesis, proliferation, and metastasis, as well as EMT in various cancer cells." (PMID 35565203, 2022).
cardiovascular disease (2 papers, 2022). "The positive control gene selected was GATA5, which has a critical role in heart development and has been implicated in multiple human cardiovascular disease aetiologies." (PMID 35548346, 2022). "GATA5 is a member of GATA family and plays an important role in cardiovascular disease." (PMID 36685890, 2022).
adenocarcinoma (1 paper, 2011). A common cancer characterized by the presence of malignant glandular cells. "We successfully identified two new subgroups of tumors with distinct DNA methylation profiles among the esophageal and gastric cardia adenocarcinomas that could be best predicted by DNA methylation of the GATA5 marker alone." (PMID 22028801, 2011).
heart disease (1 paper, 2022). "Despite this, no significant common variant associations with heart disease were found, although rare loss-of-function mutations in GATA5 have been reported to cause congenital heart defects." (PMID 35548346, 2022).
immune disorder (1 paper, 2015). "However, our experimental observations suggest that GATA5 has no direct major effect on the immune system, and that macrophage infiltration in Gata5-null mice was secondary to increased BP and specific to the kidney, not the reflection of a systemic immune disorder." (PMID 26617239, 2015).
infection (1 paper, 2023). The state of being infected such as from the introduction of a foreign agent such as serum, vaccine, antigenic substance or organism. "These are involved in smooth-muscle function (FGFR1, GATA5 and STIM1), tissue organization (ADAMTS10), alveolar and epithelial function (ABCA3 and CLDN18), and inflammation and immune response to infection (CFH, CYTL1, HMCN1, LRBA and STIM1)." (PMID 36914875, 2023).
GATA5 also shares sentences with these, for which no sentence is quoted: atrial septal defect (2 papers); clear cell renal cell cancer (2); pulmonary valve stenosis (2); Tetralogy of Fallot (2); ventricular septal defect (2); acute myocardial infarction (1); angina (1); aortic valve stenosis (1); Arrhythmia (1); atrial fibrillation (1); cardiomyopathy (1); cervical cancer (1); double outlet right ventricle (1); esophageal cancer (1); esophageal squamous cell carcinoma (1); essential hypertension (1); gastric adenocarcinoma (1); glaucoma (1); H. pylori (1); hematologic disorder (1); hypertensive nephropathy (1); hypertrophy (1); inflammatory bowel disease (1); inherited retinal dystrophy (1); ischemic heart disease (1); Müllerian agenesis (1); Obesity (1); pancreatic cancer (1); pulmonary arterial hypertension (1); Pulmonary Stenosis (1).
A further 3 diseases each share a sentence with GATA5 in 1 paper.